MPO (myeloperoxidase)
Diseases named in the same sentence as MPO in open-access papers (continued):
Sharing a sentence is not in itself a finding about the gene and the disease.
COVID-19 (continued). "To assess the factors involved in the reduced intracellular killing capacity of acute-phase COVID-19 neutrophils, we analyzed key neutrophil effector responses such as reactive oxygen species (ROS) and myeloperoxidase (MPO) production, cell death and neutrophil extracellular traps (NETs) formation." (PMID 35007290, 2022). "As such, MPO has been studied extensively as a marker of inflammation in COVID-19." (PMID 35326373, 2022). "Compared to AMC, only COVID-19 patients showed elevated MPO (p < 0.0001)." (PMID 36139476, 2022). "Patients with severe COVID-19 show significantly higher levels of neutrophil extracellular traps (NETs), circulating double stranded DNA (dsDNA), histone–DNA complexes, neutrophilic elastase, and myeloperoxidase (MPO)–DNA complexes." (PMID 36297092, 2022). "Notably, higher serum levels of cell-free DNA and MPO/DNA complexes were detected in more severe COVID-19 patients." (PMID 33982161, 2022). "Furthermore, other indirect markers of NETosis have already been studied in patients with COVID-19 such as total DNA, myeloperoxidase (MPO)–DNA complexes, and citrullinated histone H3." (PMID 36619613, 2022). "However, thrombi of COVID-19 patients showed increased neutrophil density (MPO+ cells) and a three-fold higher Neutrophil-to-Lymphocyte Ratio (tNLR)." (PMID 35105380, 2022). "The levels of serum H3Cit, MPO-DNA, DNA, and calprotectin were still higher in COVID-19 patients with both arterial thrombosis and VTE than those without thrombotic events, despite prophylactic anticoagulation was prescribed at the time of diagnosis of thrombotic events." (PMID 36224604, 2022). "In patients hospitalized with COVID-19, Ang-2, IL6, and MPO were associated with mortality, but without conclusive evidence of specificity for COVID-19." (PMID 36403043, 2022). "Our findings suggest that NET formation and MPO secretion could follow different pathways in COVID-19." (PMID 36289900, 2022). "The highest values of NET markers were found in the plasma of severe COVID-19 patients, which showed significant differences from HI in the analysis of NE (45.3 ng/ml vs 12.88 ng/ml, p < 0.000001), MPO (90.85 ng/ml vs 11.91 ng/ml, p < 0.000001), and cirDNA (116 ng/ml vs 5.76 ng/ml, p < 0.000001)." (PMID 36443816, 2022). "Indeed, levels of soluble CD14 (sCD14; monocyte inflammation marker) and myeloperoxidase (MPO; neutrophil inflammation marker) were significantly higher during severe COVID-19 compared to mild and control groups." (PMID 34177935, 2021). "This could indicate that in COVID-19 NET formation is better reflected by the release of neutrophil-specific markers such as NE or MPO/DNA complexes, while cfDNA could relate to cellular damage in a broader sense." (PMID 34344929, 2021). "Interestingly, enhanced expression and circulation of autoantigens like MPO or PRTN3 has also been observed in COVID-19 patients, and the levels of expression of some of these autoantigens correlate with disease severity." (PMID 34512643, 2021). "As there were higher degrees of correlation of cfDNA with clinical parameters than MPO-DNA, it may be directly related to leukopenia and tissue damage in patients with COVID-19." (PMID 33557911, 2021). "Mechanistically, the authors suggested that by catalysing the generation of the oxidant hypochlorous acid and consuming nitric oxide, MPO may contribute to COVID-19 pathology by promoting oxidative stress, vasoconstriction, tissue injury and cell death." (PMID 34149717, 2021). "The neutrophil proteases PRTN3 (proteinase-3) and MPO (myeloperoxidase) and the neutrophil-derived protein AZU1 were associated with severe disease, indicating that neutrophil activation and degranulation are features of severe COVID-19." (PMID 33704068, 2021). "In addition, a study by Wang and colleagues demonstrated at the transcriptional level the activation of several NETs-associated genes such as myeloperoxidase (MPO) and neutrophil elastase (NE) in individuals infected with COVID-19." (PMID 34899746, 2021).
COVID-19 (continued). "Confirming previous findings, increased MPO level reflected COVID-19 severity." (PMID 34276672, 2021). "Taken together, luteolin-mediated anti-PC and COVID-19 benefits could be accomplished through regulation of core gene activities, especially MPO and FOS." (PMID 35178029, 2021). "Furthermore, we evaluated serum levels of conventional primary granule components, i.e., myeloperoxidase (MPO) and neutrophil elastase (NE), and found them to be increased in COVID-19 serum." (PMID 33003471, 2020). "Moreover, neutrophil derived EVs carrying tissue factor (TF+ MPO+) have been shown to be elevated in COVID-19 patients as well as in inflammatory conditions, such as anti-neutrophil cytoplasm antibody (ANCA)-associated vasculitis (AAV), and they are associated with increased thrombin generation." (PMID 39178205, 2024). "Moreover, a semi-quantitative analysis of MPO expression was performed using 400x images, and showed a significant upregulation in the lung tissues of patients with COVID-19 patients compared to the controls, with positive cell counts of 43.3 ± 28.5 vs 12.6 ± 6.9." (PMID 38882332, 2024). "Plasma MPO-DNA complexes may be a particularly relevant marker for COVID-19 thrombogenesis." (PMID 38397474, 2024). "Interestingly, when serum of COVID-19 patients is incubated with neutrophils isolated from healthy individuals in vitro, the release of DNA-bound MPO enzyme and extracellular chromatin structures with neutrophils elastase were observed, suggesting a remarkable NET trigger." (PMID 35757770, 2022). "Enhanced neutrophil activation profiles strongly predict critical COVID-19 illness, and severe patients present with higher plasma levels of neutrophil effectors such as neutrophil extracellular traps (NETs) and granule proteins such as elastase, myeloperoxidase (MPO), and cathepsin." (PMID 36685578, 2022). "Indeed, MFI of MPO expression on LDGs was higher in these individuals, suggesting that COVID-19 convalescents may possess more abundant granules within the neutrophils." (PMID 36591237, 2022). "Interestingly, neutrophil aggregation and elevated levels of pro-inflammatory cytokines are associated with disease severity in patients with COVID-19, and proteomic analysis confirmed that the level of MPO in the nasopharyngeal tissue of COVID-19 patients was also increased." (PMID 35912260, 2022). "Thus, inhibiting the chlorinating activity of MPO and/or direct scavenging of HOCl in the early stages of infection could be helpful to the patients with COVID-19." (PMID 33390833, 2021). "In contrast, G-MDSC from severe COVID-19 patients had increased expression of genes associated with granulocyte functions/degranulation and chronic inflammation including Arg1, MMP8, MMP9, S100A8 and A9, MPO, IL18RA, elastase, PRTN3 (azurophilic granule protein 7)." (PMID 34341659, 2021). "MPO inhibitors might have a role in reducing neutrophil-mediated tissue injury in COVID-19." (PMID 33704068, 2021). "In addition, analytes which are traditionally used to measure NETs (MPO and NE) will also be run to further elucidate the role that NETosis plays in COVID-19, which could lead to new therapeutic targets." (PMID 33816549, 2021). "Furthermore, the genes ELANE, AZU1, MPO, PRTN3, CTSG, and TCN1 were shown to be significantly altered in patients with COVID-19, and our automatically prepared knowledge base highlights all of them as associated with COVID-19 with “medium” or “low” confidence." (PMID 33055059, 2020). "A previous study showed that the systemic concentrations of neutrophil chemokines (CXCL1/8), myeloperoxidase levels, and nasal IL17D transcription are correlated with the functional severity of COVID-19." (PMID 40362649, 2025). "A trial involving DNase I in COVID-19 (NCT04402970) showed modest benefit in improving oxygenation and decreasing DNA:MPO complex in BALF, with limitation to the time of drug delivery." (PMID 40733019, 2025).
COVID-19 (continued). "Furthermore, plasma levels of markers considered specific, such as MPO-DNA appear to be less sensitive in discriminating severity than other NETs measurement methods, such as NETosis induction in plasma samples, as has been recently reported in patients with COVID-19." (PMID 38243237, 2024). "For myeloperoxidase (MPO) the levels were markedly higher in PUUV and HC PMNs than in COVID-19 or PUUV LDGs." (PMID 39011044, 2024). "In patients with COVID-19, NET markers (such as MPO-DNA complexes, and citrullinated histone H3) have been discovered to be overexpressed in the sera, and their levels positively correlate with the severity of COVID-19." (PMID 38882332, 2024). "A recent study found a much stronger relationship between COVID-19 severity (and long COVID) and increased NETosis-induction capacity measured ex vivo, than that of circulating NET-specific marker levels (MPO-DNA complex)." (PMID 38243237, 2024). "Another study showed elevated levels of kinin peptides and myeloperoxidase (MPO)–DNA complexes, a NET marker, in the BALF of COVID-19 patients." (PMID 38400022, 2024). "ICU COVID-19 patients showed higher levels of NET markers (MPO, MPO-DNA, and histone H3) and cell-free DNA that were strongly correlated with CRP, D-dimer, and LDH, while the expression of histone H3 was associated with thromboembolic events." (PMID 37896963, 2023). "In summary, the present study demonstrates the increase in nasopharyngeal MPO, ADA, CCL22, TNFα, and IL-6 mRNA expression in COVID-19 patients." (PMID 36482706, 2023). "In the sera of hospitalized COVID-19 patients, an increase in all NET indicators (cfDNA, MPO-DNA, and Cit-H3) was found." (PMID 37762464, 2023). "COVID-19 vaccine induces ANCA-GN and AAV, possibly through molecular mimicry, stimulating productions of MPO-ANCA and PR3-ANCA via the adaptive immune system, likewise inducing antiviral neutralizing antibodies." (PMID 37243087, 2023). "Plasma, neutrophils, and lung fluids from COVID-19 patients showed increased markers of neutrophil activation and NET components, including cit-H3, myeloperoxidase (MPO), and the MPO-DNA complex." (PMID 37628764, 2023). "Differences in EG shedding between COVID-19 plasma and purified MPO-H2O2 catalysation highlight the complexity in MPO induced EG breakdown." (PMID 37147421, 2023). "We analysed the serial MPO, ADA, CCL22, TNFα, and IL-6 mRNA expression in nasopharyngeal specimens of 154 COVID-19 and 163 control hospitalized patients in the fifth wave of COVID-19 in Hong Kong." (PMID 36482706, 2023). "Despite similar levels of the myeloperoxidase (MPO)–DNA complex between mild versus control and moderate versus severe COVID-19 cases, histone–DNA was higher in the moderate and severe COVID-19 cases than the mild cases and the control." (PMID 35406667, 2022). "Confirmatory IF-staining detected intra-alveolar and interstitial DEspR+CD11b+ neutrophils and macrophages in ARDS and COVID-19-ARDS lung tissue sections, as well as DEspR+MPO+ neutrophils and macrophages in COVID-19-ARDS lung tissue section." (PMID 35379853, 2022). "ELISA of an independent group of patients have confirmed that MPO, LCN2 and DEFA3 are increased in COVID-19 ICU/F patients when compared to HDand observed that LCN2 and DEFA3 can discriminate ICU/F from non-ICU COVID-19 patients." (PMID 36348270, 2022). "In COVID-19, major NET protein cargos of NETs (i.e., NE, MPO, and histones) are significantly elevated." (PMID 35309344, 2022). "The levels of DNA, myeloperoxidase (MPO)-DNA complexes and citrullinated histones (H3Cit) increased two-fold in COVID-19 patients compared to healthy controls." (PMID 36466841, 2022). "Furthermore, the levels of NET products and IL-8 observed in plasma could be used as biomarkers to determine the disease severity of COVID-19 patients, particularly NE and MPO–DNA complexes, which are mainly produced by neutrophils and more specific to NET formation." (PMID 35563204, 2022).
COVID-19 (continued). "Levels of circulating myeloperoxidase (MPO)-DNA complexes, a marker of NETs levels, were observed to be increased in symptomatic COVID-19 patients." (PMID 36140548, 2022). "We next quantified the levels of circulating cell-free DNA (cfDNA) and NETs (myeloperoxidase-DNA [MPO-DNA] complexes) in patient plasma and again observed significantly elevated NETs and cfDNA in the plasma of patients with COVID-19, as previously reported." (PMID 34908534, 2022). "Plasma NE, MPO, and cirDNA concentrations were significantly elevated in the SLE, mCRC, and COVID-19 patients compared to HI." (PMID 36443816, 2022). "The increase in the levels of histone H4, MPO, LCN2, PGLYRP1and DEFA3 detected in our proteomic analysis strongly support the observation that excessive NET formation occurs in severe COVID-19 patients." (PMID 36348270, 2022). "In line with previous findings, LDGs from COVID-19 convalescents demonstrated more mature granulocytes with higher expression of CD10, CD16, and MPO, in combination with enhanced NET production." (PMID 36591237, 2022). "Patients with MIS-C showed higher plasma levels of C reactive protein (CRP), MPO, IL-6, and of the pro-inflammatory chemokines CXCL8 and CCL2 than COVID-19 children." (PMID 33841438, 2021). "MPO and TSHR were the only two autoantigens overexpressed in lung autopsies and were shared between the lung and blood of severe COVID-19 patients." (PMID 34276672, 2021). "Increased serum levels of neutrophil-derived MPO-DNA and citrullinated histone H3, both NET degradation products, closely parallel lung distress and predict COVID-19 severity." (PMID 34031543, 2021). "In a cohort study, plasma MPO-DNA complexes defined as NETs, platelet factor 4, RANTES (CCL5) and selected cytokines were measured in plasma samples from COVID-19 patients (n = 33) and age- and sex-matched controls (n = 17)." (PMID 34359859, 2021). "Myeloperoxidase-DNA and citrullinated histone H3, surrogate markers of NET formation, showed high levels in COVID-19, especially in patients on ventilators or admitted to the ICU." (PMID 34177896, 2021). "The level of three autoantigens, MPO, PRTN3, and PADI4, were higher in the blood of severe compared to mild COVID-19." (PMID 34276672, 2021). "In severe COVID-19, a similar pattern was observed but weakly lower on SCGF and MPO and weakly higher on IL-1α and IL-17." (PMID 34238349, 2021). "To validate our in-silico analysis, we next measured plasma protein levels of two autoantigens of MPO and PRTN3 in severe and asymptomatic COVID-19." (PMID 34276672, 2021). "Comparison of COVID-19 blood transcriptomic with IAV and RSV revealed that MPO, PRTN3, and PADI4 were selectively upregulated in coronavirus infections, SARS-CoV-1 and SARS-CoV-2, while TSHR and PTPRN2 autoantigens were distinctive to SARS-CoV-2 infection." (PMID 34276672, 2021). "In studying sera from COVID-19 patients, the authors detected higher NET markers (cell-free DNA, myeloperoxidase (MPO) DNA complexes, and/or citrullinated histone H3)." (PMID 34065210, 2021). "Markers of NET formation, including cell free DNA, myeloperoxidase-DNA complexes (MPO-DNA), and citrullinated histone-3 (citH3), were elevated in the COVID-19 patients in comparison to healthy controls." (PMID 33378321, 2021). "To validate our in-silico analysis, we measured plasma protein levels of two autoantigens, MPO and PRTN3, in severe and asymptomatic COVID-19." (PMID 34276672, 2021). "Sera from COVID-19 patients show elevated levels of markers for NET formation, such as circulating extracellular DNA (ecDNA), neutrophil elastase (NE) activity or myeloperoxidase-DNA (MPO-DNA), and these levels correlate with disease severity." (PMID 33322797, 2020). "MPO and elastase mediated NETs contribute to the severity in COVID-19 and result in ARDS in severe COVID-19 patients." (PMID 33584719, 2020). "MPO could correlate with APACHE and SOFA scores in septic patients in addition to COVID-19 patients." (PMID 40731775, 2025).
COVID-19 (continued). "Of a particular relevance to the present topic, one mechanism could implicate the clearance of MPO that is abundant within NETs, potentially altering LDL oxidation and ameliorating COVID-19 symptoms." (PMID 40842550, 2025). "Thrombi from COVID-19 patients did exhibit increased neutrophil density (MPO+ cells) and neutrophil-to-lymphocyte ratios-both had good discriminative ability to distinguish thrombi from patients with COVID-19 from those without COVID-19." (PMID 39179952, 2025). "While the serum level of MPO is elevated in non-hospitalized COVID-19 patients compared HCs, it does not experience significant change between hospitalized COVID-19 and HCs." (PMID 41209585, 2025). "In our previous research, we found that severe septic COVID-19 patients hospitalized with poor prognosis exhibited excessive NETosis, as evidenced by elevated levels of cell-free DNA (cfDNA), NET, heightened myeloperoxidase (MPO) activity, and increased NEs." (PMID 39894864, 2025). "In conjunction with this finding, we observed that MPO-DNA, H3cit, and H3cit-DNA complexes correlated with CRP and the neutrophil/lymphocyte ratio, both being key biological markers of disease severity in all COVID-19 patients." (PMID 38454482, 2024). "Although there are significant differences in terms of age, co-morbidities, and blood parameters, multivariate analysis still showed that the expression of MPO, ADA, CCL22, TNFα, and IL-6 mRNA in nasopharyngeal specimens is higher in COVID-19 patients when compared with the control group." (PMID 36482706, 2023). "The amount of plasma MPO–DNA complexes, soluble and cellular factors that trigger NETs, is increased in patients with severe COVID-19, and pulmonary autopsies confirmed the presence of NET-containing microthrombi in deceased COVID-19 patients." (PMID 37896963, 2023). "Neutrophils were also identified in the testes of COVID-19 patients; however, their myeloperoxidase activity (MPO assay) was not altered when compared to Controls." (PMID 36797789, 2023). "With respect to circulating NETs, only NE-DNA complexes, but not MPO-DNA complexes were elevated in mild (p < 0.0001) and moderate/severe disease (p = 0.0002) COVID-19 patients compared to HC." (PMID 37248708, 2023). "Therefore, our data provide a link between high levels of MPO and increased lipid oxidation at the site of inflammation, pointing to the possibility that LPOs might be suitable new drug targets in future therapeutic approaches for COVID-19 patients with severe infection." (PMID 36768969, 2023). "In COVID-19 ICU patients, dialysis use was associated with reduced levels of MPO-DNA (p = 0.01, data not shown), and presence of ARDS was associated with elevated calprotectin levels (p = 0.04, data not shown)." (PMID 37248708, 2023). "In COVID-19 moderate patients, only total DNA concentration, but not MPO-DNA nor H3Cit levels, was higher in non-survivors than that in survivors, but the low number of events deters from firm conclusions." (PMID 35371025, 2022). "Levels of Nu.Cit-H3R8, Cit-H3 and MPO, either normalized by neutrophil count or not, as well as NE/neutrophils, are not different in septic shock and critical COVID-19 cohorts, suggesting similar PAD4 activity in these groups." (PMID 36008932, 2022). "When the blood transcriptomic profiles of patients with mild COVID-19 were compared with the profiles from patients with moderate or severe COVID-19, CEACAM8, MMP8, ELANE, LTF, CEACAM6 and MPO were consistently amongst the top SDE genes, with levels increasing with severity and high LFCs." (PMID 35844004, 2022). "Importantly, the identification of the DEspR+CD11b+ neutrophil-subset in whole blood is supported by detection of DEspR+CD11b+ and DEspR+MPO+ neutrophils and monocyte/macrophages in postmortem lung tissue sections from ARDS and COVID-19-ARDS." (PMID 35379853, 2022).